ARHGAP11A (Rho GTPase activating protein 11A)
Diseases named in the same sentence as ARHGAP11A in open-access papers (continued):
Sharing a sentence is not in itself a finding about the gene and the disease.
glioblastoma (2 papers, 2013 to 2023). The most malignant astrocytic tumor (WHO grade IV). "A recent report showed that ARHGAP11A expression is increased and translocated to nucleus upon DNA damage in human glioblastoma." (PMID 24386239, 2013). "However, we revealed that ARHGAP11A was up-regulated in various cancers including glioblastoma, whereas almost ARHGAP isoforms were down-regulated." (PMID 24386239, 2013).
renal cell carcinoma (2 papers, 2023 to 2024). "ARHGAP11A was found to promote the proliferation and migration of renal cell carcinoma by inhibiting the tumor immune microenvironment." (PMID 38783033, 2024). "ARHGAP11A knockdown suppressed renal cell carcinoma (RCC) cell proliferation, colony formation, and migration, suggesting the promoting role of ARHGAP11A on RCC development." (PMID 37175461, 2023).
Alzheimer disease (1 paper, 2024). A progressive, neurodegenerative disease characterized by loss of function and death of nerve cells in several areas of the brain leading to loss of cognitive function such as memory and language. "More importantly, ARHGAP11A may contribute to Alzheimer’s disease pathology by mediating Amyloid-β generation and Amyloid-β oligomer neurotoxicity." (PMID 39348415, 2024).
cervical cancer (1 paper, 2023). A primary or metastatic malignant neoplasm involving the cervix. "Moreover, based on TCGA cancer data given in Results, ARHGAP11A and ARHGAP11B are highly overexpressed in cervical cancers, another area where estrogen and progesterone play important roles." (PMID 38046902, 2023).
kidney cancer (1 paper, 2021). Primary or metastatic malignant neoplasm involving the kidney. "In contrast, the ARHGAP11A expression was lower in kidney cancer when compared with normal kidney tissue." (PMID 34733886, 2021).
liver cancer (1 paper, 2017). An epithelial or non-epithelial malignant neoplasm that arises from the liver. "More importantly, the discovery of the HOXD-AS1/miR19a/ARHGAP11A signaling axis has provided new knowledge for understanding the molecular basis of liver cancer and for the development of new diagnostic and therapeutic strategies." (PMID 28724429, 2017). "Therefore, our investigation provides a possible explanation for miR19a downregulation contributing to liver cancer progression, specifically the upregulation of the miR19a target gene, ARHGAP11A." (PMID 28724429, 2017).
lymphoma (1 paper, 2021). A malignant (clonal) proliferation of B- lymphocytes or T- lymphocytes which involves the lymph nodes, bone marrow and/or extranodal sites. "We revealed that expression levels of ARHGAP11A were elevated in breast, cervical, colorectal, gastric, ovarian cancers, lymphoma and sarcoma relative to normal tissues." (PMID 34733886, 2021).
metastatic cancers (1 paper, 2017). A carcinoma which has spread from the original site of growth to another anatomic site. "Intriguingly, a significant upregulation of ARHGAP11A was observed in metastatic cancers compared to the non-metastatic cancer tissues (p<0.01)." (PMID 28724429, 2017).
Prader-Willi syndrome (1 paper, 2012). "Although the mechanism is unclear, sleep disturbances are characteristic of Prader Willi Syndrome, caused by a deletion in 15q11-q13 that encompasses ARHGAP11A." (PMID 23251661, 2012).
pulmonary arterial hypertension (1 paper, 2020). Pulmonary arterial hypertension (PAH) is a group of diseases characterized by mean pulmonary artery pressure >20 mmHg and elevated pulmonary arterial resistance leading to right heart failure. "Among them, KIF23 and ARHGAP11A were down-regulated in pulmonary arterial hypertension patients, which might have a protective role in PAH." (PMID 32886110, 2020).
renal carcinoma (1 paper, 2023). A carcinoma arising from the epithelium of the renal parenchyma or the renal pelvis. "In renal cancer-bearing mice, the ARHGAP11A low-level group responded more effectively to anti-PD-L1 plus anti-CTLA-4 immunotherapy." (PMID 37175461, 2023). "In addition, by analyzing gene expression profiles from renal cancer-bearing mice treated with an anti-PD-L1 and anti-CTLA-4 combination therapy, we confirmed that renal cancer-bearing mice responding to immunotherapy had a lower level of ARHGAP11A." (PMID 37175461, 2023).
Salmonella Infections (1 paper, 2024). Infections with bacteria of the genus SALMONELLA.
skin cutaneous melanoma (1 paper, 2021). "Moreover, the transcriptional expression level of ARHGAP11A in metastatic lesion of skin cutaneous melanoma (SKCM." (PMID 34733886, 2021).
stomach adenocarcinoma (1 paper, 2021). "The expression of ARHGAP11A was found significantly higher in gastrointestinal cancers including stomach adenocarcinoma." (PMID 34733886, 2021).
cancer (14 papers, 2013 to 2024). A tumor composed of atypical neoplastic, often pleomorphic cells that invade other tissues. "First of all, it is surprising that cell mobility and thus cancer invasiveness are critically linked to the cell cycle via the action of ARHGAP11A." (PMID 24386239, 2013). "It is thus tempting to speculate that loss of GID4 stabilizes ARHGAP11A in these cancer cells, thereby contributing to tumor progression." (PMID 39389782, 2024). "In various pathological conditions, ARHGAP11A emerges as a multifaceted regulator involved in cancer cell mobility, Aβ neurotoxicity, and angiogenesis, making it a potential therapeutic target." (PMID 38397233, 2024). "This indicated that patients with high ARHGAP11A level and immune infiltration tended to have a prominent T cell dysfunction signature, which impaired the ability of cytotoxic T cells to eliminate cancer cells." (PMID 37175461, 2023). "We next identified the prognostic value of ARHGAP11A in various cancers by using the Prognoscan and Kaplan-Meier plotter." (PMID 34733886, 2021). "We found that through bioinformatic analysis ARHGAP11A is highly expressed in a variety of cancer tissues, and Fan's research also confirmed this." (PMID 34912455, 2021). "Subgroup analysis is needed to confirm the prognostic value of ARHGAP11A expression in various types of cancer." (PMID 34733886, 2021). "Based on gene ontology categories, we extracted genes related to cellular movement from the 1,656 candidates and found that an uncharacterized Rho GTPase-activating protein (RhoGAP), Arhgap11a, was preferentially expressed in green S/G2/M phase cancer cells." (PMID 24386239, 2013). "By using intravital multiphoton imaging techniques, we showed that SH cells were less motile than control cells in subcutaneously inoculated tumors, clearly demonstrating that ARHGAP11A regulates the motility of HCT116 cancer cells in vivo." (PMID 24386239, 2013). "The present study suggests that ARHGAP11A, a cell cycle-dependent RhoGAP, is a critical regulator of cancer cell mobility and is thus a promising therapeutic target in invasive cancers." (PMID 24386239, 2013). "Next, we examined the effect of Rho inhibition by ARHGAP11A on the control of cancer cell morphology and mobility." (PMID 24386239, 2013). "Blockade of Arhgap11a would therefore be a conceptually novel anti-cancer therapy that would be expected to inhibit cancer cell mobilization and invasion into surrounding tissues." (PMID 24386239, 2013). "Expression of ARHGAP11A in cancer cells suppressed RhoA-dependent mechanisms, such as stress fiber formation and focal adhesion, which made the cells more prone to migrate." (PMID 24386239, 2013). "Next, we evaluated the potential of ARHGAP11A as a novel therapeutic target for inhibition of cancer progression." (PMID 24386239, 2013). "In fact, we showed that ARHGAP11A promotes migration and invasion of cancer cells, by inhibition RhoA and resultant counter-activation of Rac1." (PMID 24386239, 2013). "Moreover, our TCGA analysis showed that ARHGAP11A has an oncogenic role in various cancers such as lung, colon, kidney, and BC, especially in TNBCs, and our TCGA data analysis revealed that all BRCA histological subtypes had overexpression in 787 IDC cases." (PMID 38046902, 2023). "Also, it was demonstrated that not only overexpression of ARHGAP11A leads to cell proliferation in BLBC but also alteration of the normal cells into the cancer phenotype." (PMID 38046902, 2023). "Also, it was revealed that applying interfering RNA- (iRNA-) based suppression to ARHGAP11A can decrease the aggressive properties of several cancers which can reveal the oncogenic role of this RhoGAP." (PMID 38046902, 2023). "Taken together, ARHGAP11A revealed dual effects on different human cancers." (PMID 34733886, 2021). "ARHGAP11A promotes colon cancer cell invasion and is the main regulator of cancer cell motility." (PMID 34912455, 2021).
cancer (continued). "This functional diversity might correlate with cancer type context, and unravel the unique role of ARHGAP11A in HCC." (PMID 30545369, 2018). "Taken together, these results show that ARHGAP11A, part of the RhoGAP family, whose members had been presumed to act as suppressors and to be deleted in cancer, is upregulated and might serve as an oncogene in HCC." (PMID 30545369, 2018). "Because HOXD-AS1 was able to upregulate ARHGAP11A expression in vitro, we next asked whether the miR19a/ARHGAP11A axis contributes to HOXD-AS1-mediated cancer cell metastasis." (PMID 28724429, 2017). "The Kaplan–Meier survival analyses demonstrated that HCC cancer patients with lower ARHGAP11A mRNA expression exhibited better prognosis compared with those patients with higher ARHGAP11A expression (Gehan-Breslow-Wilcoxon test, p = 0.0094, log-rank test, p = 0.059)." (PMID 28724429, 2017). "RNAi-based inhibition of Arhgap11a reduced the invasion and in vivo expansion of cancers." (PMID 24386239, 2013). "Next we examined the role of ARHGAP11A in in vivo motility of inoculated cancer cells." (PMID 24386239, 2013). "Here, we propose that ARHGAP11A may be a good novel candidate as a target against invasive cancers, namely blocking cancer cell progression by inhibiting invasive properties." (PMID 24386239, 2013). "Consequently, ARHGAP11A, a RhoGAP preferentially expressed in invasive human cancers, may become a promising target for cancer therapy." (PMID 24386239, 2013). "Furthermore, ARHGAP11A is specifically increased in a wide array of cancers, compared as other ARHGAP family members, suggesting the possibility that we could develop therapeutically effective inhibitors with less adverse effects." (PMID 24386239, 2013). "In our study, we first performed a bioinformatic investigation regarding the role of these two RhoGAP paralog genes (i.e., ARHGAP11A and ARHGAP11B) in BC and different cancers and their correlations with each other and with other genes in different cancers." (PMID 38046902, 2023). "Our TCGA data analysis revealed higher expression of ARHGAP11A and ARHGAP11B in various cancers comprising BCs." (PMID 38046902, 2023). "In summary, ARHGAP11A, as a RhoGAP, suppressed Rho-dependent phenomena, such as focal adhesion and stress fiber formation, in HCT116 cancer cells." (PMID 24386239, 2013). "Moreover, our data found that ARHGAP11A and ARHGAP11B were also overexpressed in almost all TCGA cancers, representing their possible protooncogenic role." (PMID 38046902, 2023). "On the other hand, ARHGAP11A was significantly overexpressed in cancer tissue compared to non-cancerous tissue in the metastatic group." (PMID 28724429, 2017). "On the other hand, we do not currently know the mechanisms by which ARHGAP11A is up-regulated in cancers." (PMID 24386239, 2013). "We confirmed that siRNA injected in vivo was incorporated into inoculated cancer cells, although we could not exclude the possibility that siRNAs against ARHGAP11A may be taken up by and act on the stromal cells surrounding the tumors." (PMID 24386239, 2013). "ARHGAP11A was previously proved to be a GAP specific for Rho, but not for Rac or Cdc42, and ARHGAP11A stimulated cancer cell motility by enhancing Rac activity." (PMID 30545369, 2018).
tumor (13 papers, 2013 to 2024). "The correlation of ARHGAP11A expression with immune infiltrates and associated gene markers was clarified by Tumor IMmune Estimation Resource and Gene Expression Profiling Interactive Analysis database." (PMID 34733886, 2021). "We used the “Similar Genes Detection” module of GEPIA2 to obtain the top 100 ARHGAP5 or ARHGAP11A correlated genes based on the datasets of all TCGA tumor and normal tissues." (PMID 38783033, 2024). "The expression level of ARHGAP11A was correlated with tumor size (p = 0.001), and tumor stage (p = 0.029)." (PMID 38783033, 2024). "The results showed that the samples with high ARHGAP11A level had more immune cell infiltration in tumor tissues." (PMID 37175461, 2023). "Other members of RhoGAPs also played a tumor-promoting or -suppressing role via mechanisms completely different from ARHGAP11A." (PMID 37175461, 2023). "ARHGAP11A promoted ccRCC cell proliferation and migration by contributing to the suppressive tumor immune microenvironment (TIME)." (PMID 37175461, 2023). "Regarding TCGA-BRCA tumor stages, our analysis revealed that ARHGAP11A and ARHGAP11B showed overexpression across BRCA cancer stages, indicating their role in tumorigenesis and invasion." (PMID 38046902, 2023). "Our results demonstrated that the expression level of ARHGAP11A (P = 0.0001) had remarkable overexpression in tumor tissues compared to normal tissues." (PMID 38046902, 2023). "We also found a highly positive correlation between ARHGAP11A expression and tumor proliferation signature score in each ccRCC sample by ssGSEA (R = 0.670, p < 0.001)." (PMID 37175461, 2023). "Analysis results for the GEO (GSE53757) and CCLE databases verified that ARHGAP11A mRNA levels were upregulated in both RCC patient tumor samples and RCC cells." (PMID 37175461, 2023). "Results showed significant differences in ARHGAP11A expression levels when compared tumor and normal tissues." (PMID 34733886, 2021). "We next investigated the correlation of ARHGAP11A expression and tumor infiltrates in Tumor IMmune Estimation Resource (TIMER) and Gene Expression Profiling Interactive Analysis (GEPIA)." (PMID 34733886, 2021). "To further confirm the influence of the change in the ARHGAP11A expression level on tumor growth in vivo, we established a subcutaneous xenograft model in nude mice by subcutaneous injection of ARHGAP11A knockout and negative control MKN45 cells." (PMID 34912455, 2021). "Both the tumor volume and weight of mice in the ARHGAP11A- knockdown group were markedly lower than those of mice in the negative control group." (PMID 30545369, 2018). "This seemed to be contradictory to the tumor-promoting role of ARHGAP11A." (PMID 37175461, 2023). "The high level of ARHGAP11A in ccRCC tissues suggested that ARHGAP11A might play a tumor-promoting role in ccRCC." (PMID 37175461, 2023). "Mechanistically, ARHGAP11A might contribute to the suppressive tumor immune microenvironment (TIME)." (PMID 37175461, 2023). "Moreover, the expressions of ARHGAP11A and Ki-67 in tumor tissues were detected by immunohistochemistry." (PMID 34912455, 2021). "The results showed that the expression level of ARHGAP11A was closely related to tumor differentiation (p < 0.05) but was not significantly correlated with age, sex, clinical stage, TNM stage, or other clinicopathological characteristics of the patients (p > 0.05)." (PMID 34912455, 2021). "Moreover, Ki-67 and ARHGAP11A staining were performed to detect the proliferation of tumor cells and the expression of ARHGAP11A." (PMID 30545369, 2018). "In vivo siRNA treatment significantly reduced tumor expansion (1471±238.5 mm for scrambled siRNA, 422.1±44.5 mm for siRNA#1, and 717.6±162.7 mm for siRNA#2 at day 28), suggesting that ARHGAP11A is a promising therapeutic target for the treatment of invasive tumors." (PMID 24386239, 2013). "Finally, we investigated the role of ARHGAP11A in tumor expansion in vivo." (PMID 24386239, 2013).
tumor (continued). "Next, we compared the expression level of two RhoGAP paralog genes (i.e., ARHGAP11A and ARHGAP11B) in tumor and normal breast samples of IDC cases and evaluated them in several reproductive, demographic, and clinicopathological factors among women with IDC." (PMID 38046902, 2023). "The results demonstrated that the expression levels of CCNE1, E2F1, ARHGAP11A, RUNX1T1 and FES displayed significant correlation with the tumor stage in patients with NSCLC." (PMID 33613291, 2021). "Then we analyzed the correlation between transcription level of CCNE1, E2F1, ARHGAP11A, RUNX1T1, FES and tumor stage in TCGA NSCLC cohort by GEPIA 2 online website." (PMID 33613291, 2021). "The variant piR-021285-mimic transfected into BC cell lines could weaken methylation of pro-invasive gene ARHGAP11A at the region of the 5' UTR/first exon CpG island, leading to increased ARHGAP11A expression and tumor cell invasiveness." (PMID 35637965, 2022). "High expression of ARHGAP11A was identified to be correlated with tumor size, differentiation, metastasis and TNM stage but not with other clinicopathological characteristics, such as gender, age, and AFP in patients with HCC." (PMID 30545369, 2018). "Thereby, we have reasons to believe that ARHGAP11A can act as an oncogene, not a tumor suppressor, in human HCC." (PMID 30545369, 2018). "In addition, clinicopathological analysis revealed that the overexpression of both genes was closely correlated with Grades III and IV (HOXD-AS1, p = 0.0381; ARHGAP11A, p = 0.0006) and with PVTT tumor invasion (HOXD-AS1, p = 0.0419; ARHGAP11A, p = 0.0079)." (PMID 28724429, 2017). "Thus, our results support the hypothesis that ARHGAP11A has an oncogenic role, rather than a tumor suppressive role, in HCC cells." (PMID 30545369, 2018). "The results showed that TRAF3IP3, WIPI1, ARHGAP11A, and RHOQ were significantly differentially expressed in normal and tumor tissue, displaying good classification performance." (PMID 36185204, 2022). "Moreover, the Tumor Immune Dysfunction and Exclusion (TIDE) analysis further showed that the group with a high level of ARHGAP11A had a higher dysfunction score, but not exclusion score for T cells." (PMID 37175461, 2023).
blood cancer (1 paper, 2021). "In addition, the high expression level of ARHGAP11A was associated with better prognosis in gastric and blood cancer, while correlated with poor prognosis in lung, bladder, breast and soft tissue cancer." (PMID 34733886, 2021).
ARHGAP11A also shares sentences with these, for which no sentence is quoted: clear cell renal carcinoma (2 papers); microcephaly (2); cyst (1); Ductal Carcinoma (1); lung adenocarcinoma (1); lymph node metastasis (1); non-small cell lung carcinoma (1); Obesity (1); ovarian carcinoma (1); sarcoma (1).